VEGFA (vascular endothelial growth factor A)
Diseases named in the same sentence as VEGFA in open-access papers (continued):
Sharing a sentence is not in itself a finding about the gene and the disease.
tumor (continued). "We confirmed these findings in the snRNA-Seq dataset, where, as expected, PECAM1 expression levels were the highest in the endothelial cell population, followed by macrophages, whereas VEGFA expression levels were highest in the macrophages and tumour cells." (PMID 41168392, 2025). "ZNF24, a crucial transcriptional repressor of VEGFA, binds to an 11 bp fragment in the proximal promoter region on the VEGFA gene, inhibiting its transcription and subsequently impeding tumor growth and invasion." (PMID 40274778, 2025). "Cancer cells metastasize from the primary tumor to distant sites via endovascular circulation, during which HIF increases VEGFA release, driving tumor angiogenesis." (PMID 39873475, 2025). "The aberrant activation of HIF‐1α is mainly responsible for the overexpression of VEGFA and contributes to tumor progression." (PMID 40515512, 2025). "Consistent with the observed inhibition of VEGFA expression in tumor cells due to SLC9A2, ELISA results confirmed a reduction in VEGFA levels in the Slc9a2 overexpression group." (PMID 40474298, 2025). "We found that QRHXF reduced the number of CD31 and VEGFA positive cells, suppressing tumor growth by inhibiting angiogenesis." (PMID 40670983, 2025). "This is in line with vascular adaptation to the tumor’s growing needs for nutrients and oxygen and with the increased expression of the vascular growth factor VegfA in both monocytes and macrophages." (PMID 41384492, 2025). "VEGFA was notably overexpressed in tumor subcluster T2, whereas VEGFC expression was observed in mCAFs and iCAFs, alongside the activation of EMT, PD‐1 signaling, YAP/TAZ signaling, and other fibrosis pathways, except Hippo signaling." (PMID 40843133, 2025). "Overall, these co‐expression networks elucidated the distinct roles of the two VEGF ligands: VEGFA contributes to tumor proliferation, whereas VEGFC potentiates desmoplasia and anticancer immunity." (PMID 40843133, 2025). "Previously, in the context of LC, an association of mutations in the EGFR/KRAS genes and an increased expression of VEGFA/VEGFR2 in tumor tissue was demonstrated." (PMID 39940785, 2025). "FTO acts as a tumor suppressor by negatively regulating VEGFA expression, highlighting its potential as a therapeutic target for HCC treatment." (PMID 40316995, 2025). "Tumor angiogenesis, the formation of new blood vessels to supply nutrients and oxygen to malignant cells, is critically regulated by vascular endothelial growth factor-A (VEGF-A)." (PMID 41229433, 2025). "In vitro, LRRC1 overexpression significantly increased the mRNA, protein, and secretory levels of VEGFA and promoted tumor-induced migration, invasion, and tube formation of HUVECs." (PMID 41369408, 2025). "As an example, the visualization of VEGFA, a pivotal angiogenic factor influencing tumor growth and metastasis, highlighted distinct abundance levels within tumor subpopulations at the cellular resolution." (PMID 40162205, 2025). "Experimental validation revealed that targeting SPHK1/S1P signaling suppresses VEGFA expression in tumor cells and M2-like macrophages, thereby reducing angiogenesis and inhibiting tumor progression." (PMID 40589755, 2025). "Tumor-derived VEGFA is known to recruit macrophages to tissue, contribute to M2 polarization, and can foster tumor growth." (PMID 39998425, 2025). "Depletion of macrophages, inhibition of JNK, or neutralization of IL-8 and VEGFA significantly suppressed tumor progression." (PMID 39972459, 2025). "While N1 marker expression remained stable, Neu2 (differentiation end) exhibited mild up-regulation of N2-associated markers, including ARG1, VEGFA, and CCL2, consistent with an immunosuppressive, tumor-promoting phenotype." (PMID 40959269, 2025). "When these gene-deficient GC cells (shNAT10-, shYAP1-, and shHIF1A- GC cells) were subcutaneously transplanted into nude mice, we examined the expression of VEGFA mRNA and the structure of the tumor vascular network." (PMID 40860183, 2025).
tumor (continued). "It suppresses abnormal angiogenesis by downregulating vascular endothelial growth factor-A (VEGF-A) in tumor tissues, thereby limiting the nutrient supply and metastatic pathways." (PMID 40642165, 2025). "The emergence of CAFs greatly influences the tumor microenvironment by releasing a plethora of cytokines, chemokines, growth factors, and exosomes such as VEGFA and CXCL12 to reciprocally complement the tumor growth." (PMID 40805183, 2025). "The addition of miR-205-5p-enriched EVs slowed the tumor growth rate and reduced the expression of VEGFA." (PMID 40302796, 2025). "Following the discovery of the key angiogenic factor VEGFA, several antiangiogenic therapies were developed to “starve” cancer by damaging a tumor’s ability to obtain nutrients by adopting the angiogenic switch." (PMID 39567756, 2025). "This miRNA cluster operates as a canonical tumor-suppressive axis by targeting genes associated with proliferation and EMT, such as BCL2, CCND1, and VEGFA." (PMID 41303609, 2025). "Tumor-bearing mice with raised TMAO levels exhibit significant tumor growth, more blood vessel formation, and increased VEGFA and CD31 concentrations." (PMID 40497987, 2025). "We, additionally, demonstrate a strong correlation between the cellular production of the pro-angiogenic growth factor, VEGFA and tumour neo-vascularisation to regorafenib." (PMID 40469193, 2025). "Anti-VEGFA therapy can improve host adaptive tumor immune responses via vascular normalization, leading to increased tumor-infiltrating lymphocytes, such as CD4+ and CD8+ T cells." (PMID 40906526, 2025). "The upregulation of circ‐RanGAP1 in GC tissues and plasma‐derived exosomes increases VEGFA expression by sponging miR‐877‐3p to enhance tumor growth." (PMID 40356340, 2025). "T3 neutrophils have the highest level of VEGFA expression, which promotes angiogenesis and tumour growth, highlighting that targeting the local neutrophil response still has great potential as an immunotherapy." (PMID 39847394, 2025). "That VEGFA and GPR65 DKO tumors show restoration of CAR T susceptibility and that this reduces the TME macrophage number and tumor burden implicate tumor-produced VEGFA as a key mediator of CAR T resistance in the B-ALL system." (PMID 39998425, 2025). "In CRC, LINC01123 drives tumor progression by regulating miR-34c-5p/VEGFA and miR-625-5p/LASP1 axes." (PMID 40255398, 2025). "Differentially gene expression analysis revealed 39 up‐regulated genes in tumours, including VEGFA, NFKBIA, S100A10 and C15orf48." (PMID 41275425, 2025). "In malignancies, VEGFA can be synthesized by diverse types of cells, such as tumor cells or stromal cells." (PMID 41369408, 2025). "As the tumor grows, increased VEGFA expression stimulates the formation of new blood vessels that provide essential nutrients to the tumor and support the spread of cancer cells." (PMID 40141978, 2025). "When these cells were injected to generate subcutaneous xenograft GC mouse models, VEGFA re-expression promoted tumor growth, hypoxia and necrosis." (PMID 40860183, 2025). "Single‐cell transcriptomic studies reveal that tumor‐associated neutrophils (TANs) infiltrating the PMN enhance LEC proliferation and lymphatic sprouting via ERK/JNK‐mediated secretion of MMP9 and VEGFA." (PMID 40470380, 2025). "Genetic or pharmacological inhibition of NAT10 with Remodelin attenuated VEGFA secretion, enhanced pericyte coverage and basement membrane integrity, and normalized tumor vasculature in syngeneic GC models." (PMID 40860183, 2025). "Although VEGFA is identified as one mechanism of tumor resistance to therapy, other pathways seem to be involved." (PMID 39998425, 2025). "Building upon our prior discovery of the NAT10/SEPT9/HIF-1α positive feedback loop driving glycolytic addiction in GC11, this work unveils a novel NAT10/XIST/YAP1/VEGFA axis governing tumor vascular ecology." (PMID 40860183, 2025).
tumor (continued). "VEGFA–KDR interaction was observed between tumor cell subclusters and immune cell types, whereas the VEGFC–KDR interaction signal was exclusive to CAF cells." (PMID 40843133, 2025). "Within the hypoxic tumor microenvironment, M2-like cells secrete a variety of proangiogenic factors including vascular endothelial growth factor A (VEGF-A), fibroblast growth factor (FGF2), TNF-α, IL-8, etc.." (PMID 40725081, 2025). "VEGFA, a key regulator of tumor angiogenesis, activates VEGFR-2 to upregulate VEGFR-3 and DLL4 in tip cells, while triggering Notch signaling." (PMID 40173050, 2025). "Depleting both monocyte-derived and lung-resident TAMs enhanced tumor response to “antiangiogenic immunotherapy” (a combination of VEGFA, angiopoietin-2, and PD1 blockade) in NSCLC models." (PMID 40475851, 2025). "This suggests that TAM-derived VEGFA promotes angiogenesis and increases vascular density in the deepest tumor zone." (PMID 40243510, 2025). "In summary, VEGFA secreted from tumor cells exhibits predominant expression starting in the TN stage." (PMID 40843133, 2025). "The macrophage lineage was further divided into predominant populations: suppressive (SPP1+, APOC1+), pro-tumour (VEGFA+, MKI67+), inflammatory (C1QC+), classical (CD14+) and non-classical cells (CD16+)." (PMID 39788719, 2025). "Among them, VEGFA stands out as the key regulator of angiogenesis, playing a critical role in promoting tumor growth, proliferation, invasion, metastasis, and drug resistance." (PMID 40821121, 2025). "Vascular endothelial growth factor A (VEGFA), which is significantly overexpressed in OS, promotes angiogenesis within the tumor microenvironment by paracrine stimulation of vascular endothelial cells." (PMID 40391083, 2025). "METTL3 also promotes tumor angiogenesis by modifying Ephrin-A receptor 2(EphA2) and vascular endothelial growth factor A (VEGFA) mRNAs with m6A, facilitating their recognition by IGF2BP2/3, stabilizing the mRNA, and enhancing protein translation." (PMID 39791162, 2025). "While VEGFA, expressed by all tumor cell types, facilitated tumor cell proliferation, the VEGFC–KDR signal was restricted to interactions between specific T1 tumor cells and other CAF subtypes, promoting the development of meCAFs." (PMID 40843133, 2025). "VEGFA exhibited the highest expression at the center of the tumor region T1, gradually decreasing in abundance towards the boundary; and was minimally expressed in the myeloid cell population outside of T1." (PMID 40162205, 2025). "This supports the idea that TNF-containing MCs have anti-tumor properties, while VEGFA+ MCs tend to favor pro-tumoral effects." (PMID 41465542, 2025). "Therapies targeting VEGFA, such as sunitinib, have shown efficacy in inhibiting angiogenesis and controlling tumor growth in HCC patients." (PMID 39852395, 2025). "Recruited macrophages not only enhance the inflammatory response in tissues, but can also promote tumor angiogenesis by secreting factors such as VEGFA, further supporting tumor growth." (PMID 39781471, 2025). "Inhibition of the synthesis of S1P in tumor cells and macrophages suppressed macrophage M2 polarization levels and reversed the pro-angiogenic phenotype by inhibiting VEGFA protein expression." (PMID 40589755, 2025). "Bevacizumab, the first large molecule targeted anti-tumor drug, specifically targets all subtypes of VEGFA, inhibiting its interaction with endothelial VEGFR and effectively suppressing tumor angiogenesis." (PMID 40821121, 2025). "There is also evidence to suggest that a reduction in TET2 protein results in increased angiogenesis in lung adenocarcinoma tumor samples through upregulation of VEGFa transcript, allowing for increased tumor growth and thus driving aggressive disease." (PMID 40116537, 2025). "Necrosis promotes the expression of VEGFa, as dying tumor cells release signals that stimulate the growth of new blood vessels." (PMID 40057490, 2025).
tumor (continued). "Consistent results were obtained for another TKI‐resistant sample showing VEGFA overexpression in tumor cell types and mutual exclusiveness of VEGFA and VEGFC." (PMID 40843133, 2025). "Through single-cell network analyses, we discovered that GPR65 deficiency reshapes tumor interactions with host macrophages by increasing tumor VEGFA levels, leading to macrophage expansion and preferential M2 polarization." (PMID 39998425, 2025). "Visium and Slide-seq overlays show that PD-L1-high tumour islands frequently abut VEGFA-rich peri-necrotic belts, while CXCL13+ tertiary lymphoid structures reside millimetres away yet harbour distinct cytokine profiles." (PMID 40959084, 2025). "In the present study, the angiogenesis associated proteins, namely VEGFA and ANG-2, were also significantly affected by sEVs, reflecting the importance of vascular remodelling in tumor growth and metastasis." (PMID 40282535, 2025). "To date, some researches have demonstrated that IFN-γ can inhibit tumor angiogenesis by downregulating integrin αVβ3, Dll4, Dll1, and vascular endothelial growth factor A (VEGF-A)." (PMID 40370455, 2025). "Taken together, these findings indicated that VEGFA in tumor cells appears to maintain tumor cell proliferation, whereas VEGFC in TME cells protects tumor cells via mCAF development with FGF signaling activation or YAP‐TAZ regulation." (PMID 40843133, 2025). "This analysis confirmed the significant correlation between FP status and larger tumour size in our xenografts (R=0.73, P=0.04), as well as the correlation of VEGFA secretion and neo-vessel induction sensitivity upon regorafenib treatment." (PMID 40469193, 2025). "One of the major strategies by which miR-1 decreases tumor growth is its direct targeting of VEGFA, a critical regulator of angiogenesis." (PMID 40429954, 2025). "Tumor tissues from high-PM areas exhibited significantly higher levels of VEGFA gene expression compared to those from low-PM areas (, [GSE165298]; [GSE268175])." (PMID 40940965, 2025). "In vivo, mice subjected to a long-term high-choline diet exhibited elevated circulating TMAO levels, increased tumor volume, enhanced angiogenesis, and upregulated expression of VEGFA and CD31." (PMID 40771692, 2025). "Macrophages were also found to be required for angiogenesis in xenografts secreting VEGFA or overexpressing zebrafish VEGFAA, suggesting that zebrafish macrophages enhance VEGFA-driven tumor angiogenesis." (PMID 40709187, 2025). "Among the mediators of tumor angiogenesis, vascular endothelial growth factor A (VEGF-A) and its receptor VEGFR-2 constitute the principal signaling axis that regulates endothelial proliferation, migration, and survival." (PMID 41409250, 2025). "ABCP combination therapy seems to effectively target VEGFA‐mediated signaling received by tumor cells from CAF subtypes." (PMID 40843133, 2025). "High expression of the key gene VEGFA drives significant angiogenesis, which has been shown to be a major driver of tumor angiogenesis in the high-scoring group in animal models." (PMID 40989165, 2025). "Golgi protein 73 (GP73), which is significantly upregulated in HCC, stimulates the production and secretion of vascular endothelial growth factor A (VEGFA) and promotes angiogenesis in the tumor microenvironment." (PMID 40881702, 2025). "Mechanistically, SLC9A2 suppresses the EMT pathway and subsequent metastasis by inhibiting STAT3Y705 while also reducing tumor cell secretion of VEGFA, thus limiting tumor angiogenesis." (PMID 40474298, 2025). "Antibodies blocking the function of vascular endothelial growth factor A (VEGFA) remain a promising therapeutic strategy, especially when combined with check-point inhibitors, but their efficacy is limited by tumor resistance." (PMID 41306516, 2025). "Anti-angiogenic drugs such as bevacizumab, which target vascular endothelial growth factor-A signaling, have shown potential in limiting tumor growth." (PMID 41400702, 2025).
tumor (continued). "This is because pathological angiogenesis, the most dominant form of tumor vascularization, is mainly dependent on secreted factors such as vascular endothelial growth factor (VEGFA) and angiopoietins." (PMID 41009691, 2025). "Circ-RanGAP1 is upregulated in the serum exosomes of GC patients and promotes tumor progression by regulating VEGFA." (PMID 40309240, 2025). "VEGFA has been shown to increase regional lymph node lymphangiogenesis, thereby facilitating tumor metastasis to the regional lymph nodes." (PMID 41028519, 2025). "VEGFR2 is selectively expressed on human FOXP3 high Tregs among CD4+ T-cells in tumor and VEGFA induces the recruitment and proliferation of Tregs via activation of VEGFR2 signaling." (PMID 39985645, 2025). "The majority of DEGs related to this pathway (ITGAV, KDR, VEGFB, AKT1, VEGFA) were downregulated in tumor cells except for HSBP1 and SHC2." (PMID 39245631, 2025). "In tumor xenografts, ALK knockdown was shown to reduce VEGFA expression, decrease tumor vessels in tumor xenografts, and control tumor growth." (PMID 41295262, 2025). "In vivo experiments were used to evaluate the effects of a JNK inhibitor, an IL-8 neutralizing antibody, and a VEGFA neutralizing antibody on tumor proliferation and the tumor microenvironment." (PMID 39972459, 2025). "Subcellular localization studies using scRNA‐seq and transcriptomics data revealed that VEGFA was predominantly expressed in tumor cells." (PMID 39823457, 2025). "VEGFA induces endothelial cell proliferation and migration and is indispensable for tumor vascularization." (PMID 40316995, 2025). "VEGFA drives tumor proliferation in responders, while VEGFC promotes resistance through TME interaction, FGF signaling, and YAP‐TAZ regulation." (PMID 40843133, 2025). "A similar pattern of gene expression persisted, where CA9 and VEGFA were upregulated within the in vivo RCC243 tumor models and ccRCC patient datasets, whereas FN1 was upregulated within cells grown in the in vitro RCC243 cell culture model." (PMID 40241258, 2025). "Secondly, they promote tumor angiogenesis by secreting pro-angiogenic factors like VEGFA and PDGF and altering the extracellular matrix to enhance vascular formation, facilitating tumor growth and the dissemination of cancer cells." (PMID 40313969, 2025). "In xenograft models, silencing RBM15, IGF2BP3, or YTHDF2 significantly reduces VEGFA expression and suppresses tumor growth." (PMID 41403702, 2025). "Unbiased cell–cell communication analyses of tumor cells with host macrophages and monocytes pinpointed VEGFA as a major communication hub specifically upregulated in GPR65 KO tumors." (PMID 39998425, 2025). "We showed that the HER2-VEGFA BsAbs but not the parental antibodies alone or in combination induced co-phagocytosis of VEGFA and HER2-overexpressing cancer cells by tumor-associated macrophages via ADCP." (PMID 40906526, 2025). "Mechanistically, collagen fosters angiogenesis by directly activating endothelial cells and increasing the expression and secretion of vascular endothelial growth factor A in tumor cells." (PMID 39823457, 2025). "VEGFA exhibits the capacity to facilitate tumor growth and metastasis through the augmentation of angiogenesis, establishing its status as a crucial biomarker in BC." (PMID 40575382, 2025). "Our data demonstrate that I-DXd selectively eliminates pro-tumor VEGFA+ TANs with high CSF3 expression within the TME, mitigating the potential counterproductive effects of G-CSF and enhancing the immunomodulatory impact of ADC therapy." (PMID 39971940, 2025). "Bevacizumab is a monoclonal antibody against vascular endothelial growth factor-A (VEGF-A), which inhibits the binding of VEGF-A to its receptors, causing regression of angiogenesis that supplies oxygen and nutrients to the tumor and induce tumor dormancy." (PMID 40297564, 2025).